CEBPA (CCAAT enhancer binding protein alpha)
Diseases named in the same sentence as CEBPA in open-access papers (continued):
Sharing a sentence is not in itself a finding about the gene and the disease.
pancreatic cancer (14 papers, 2013 to 2024). "Through PPI construction, we identified several genes, including mRNA (CAP2, SLC22A3), miRNA (miR-9985, miR-27, miR-548), and TFs (CEBPA), involved in the prognosis mechanism of pancreatic cancer." (PMID 37857015, 2023). "Herein, we developed a tTR14-decorated tFNA nanocarrier to specifically deliver exogenous saRNA targeting the CEBPA gene (CEBPA-saRNA) to pancreatic cancer cells, aiming to activate the tumor suppressor CEBPA and its downstream effectors to inhibit tumor cell proliferation." (PMID 38965606, 2024). "A study reported that CEBPA could promote the proliferation, invasion and migration of pancreatic cancer cells, and upregulation of CEBPA can be induced by KDM6B knockdown." (PMID 37857015, 2023). "Treatment of subcutaneous pancreatic mouse tumor model or the advanced liver-metastatic pancreatic cancer model with the CEBPA-saRNA aptamer conjugate resulted in a significant reduction in tumor growth, mediated by the increase of p21 gene which is downstream of CEBPA transcriptional activation." (PMID 34770939, 2021).
gastric cancer (13 papers, 2014 to 2024). A primary or metastatic malignant neoplasm involving the stomach. "Additionally, CEBPA has been identified as a gene with high frequency mutations in hepatocellular adenocarcinoma of the stomach (a type of gastric cancer)." (PMID 34712617, 2021). "Based on dataset GSE54129, involving 111 gastric cancer and 21 normal mucosa samples, we identified four TFs including CREB1, BPTF, GATA6 and CEBPA with high DR value among top 1% DRGs." (PMID 35421923, 2022). "It has been reported that ecCEBPA levels are upregulated in gastric cancer tissues compare to noncancer ones, suggesting that, as consequence, also CEBPA gene transcription increases; indeed, one of the CEBPA target genes, the lncRNA UCA1, is upregulated in gastric cancer tissues." (PMID 29443889, 2018).
liver fibrosis (13 papers, 2012 to 2026). "All these data indicate that induction of Spp1 gene expression by hepatocyte CEBPA deficiency predominantly contributes to the enhanced MASH-associated liver fibrosis." (PMID 38557493, 2024). "Further, when macrophages were depleted by 4-week clodronate dosing, the effect of scAAV8-U6-shSpp1 in rescuing hepatocyte CEBPA deficiency–enhanced liver fibrosis was found comparable to that in control vehicle-dosed mice." (PMID 38557493, 2024). "Forced hepatocyte-specific CEBPA expression reduced MASH-associated liver fibrosis." (PMID 38557493, 2024). "Thus, hepatic SPP1 expression strongly tracks with liver fibrosis both in human and in hepatocyte CEBPA-deficient mice during MASH progression." (PMID 38557493, 2024). "Hepatocyte CEBPA deficiency at the progressive stage of MASH promotes liver fibrosis." (PMID 38557493, 2024). "In summary, the current findings reveal a key role of hepatocyte CEBPA in restricting the liver fibrosis progression and support the application of AAV-based therapies for the treatment of MASH-associated liver fibrosis." (PMID 38557493, 2024). "Given the significant roles of CEBPA in liver fibrosis, COPD, and lung fibrosis, we aim to understand in depth how the loss of CEBPA contributes to the depletion of AT2 cells and the promotion of lung fibrosis." (PMID 39012710, 2024). "Temporal and spatial hepatocyte-specific CEBPA loss at the progressive stage of MASH in CebpaΔHep,ERT2 mice functionally promoted liver fibrosis." (PMID 38557493, 2024). "Several studies have shown that CEBPα regulates activation of hepatic stellate cells which play key roles in hepatic fibrosis." (PMID 23226395, 2012). "CEBPA is also expressed in hepatocytes and regulates glucolipid homeostasis; however, the role of hepatocyte-specific CEBPA in modulating liver fibrosis progression is largely unknown." (PMID 38557493, 2024). "Further, in the presence of scAAV8-U6-shSpp1, hepatocyte CEBPA deficiency failed to significantly enhance the HFCFD-induced liver fibrosis." (PMID 38557493, 2024). "Hepatocyte CEBPA/SPP1 axis modulates CCl4-induced liver fibrosis." (PMID 38557493, 2024). "While CEBPA is expressed in hepatocytes and is a modulator of glucolipid homeostasis, whether and how hepatocyte-specific CEBPA alters the progression of liver fibrosis remains to be explored." (PMID 38557493, 2024). "Given that CEBPA mRNA levels were decreased by about 50% both in human patients and in mice, hepatocyte heterozygous CEBPA-KO (CebpaΔHep,f/+) mice were used to test whether a reduction of CEBPA affected the extent of liver fibrosis." (PMID 38557493, 2024). "However, it is still possible that hepatocyte CEBPA deficiency increases hepatocellular cell death during the early stages of MASH, which may contribute to the enhanced liver fibrosis phenotype." (PMID 38557493, 2024). "Hepatic HES1 mRNA was positively correlated with liver fibrosis in humans, and recombinant human HES1 overexpression repressed transactivation of the CEBPA gene." (PMID 38557493, 2024). "Similarly, 24-week HFCFD-fed CebpaΔHep,ERT2 mice treated with tamoxifen for the last 12 weeks, developed enhanced liver fibrosis while scAAV8-U6-shSpp1 rescued the hepatocyte CEBPA deficiency-enhanced liver fibrosis without changing other biochemical parameters." (PMID 38557493, 2024). "AAV8-TBG-Cebpa increased hepatic Cebpa mRNA and CEBPA protein, while decreased hepatic Spp1 mRNA, serum OPN, hepatic lipid accumulation, and liver fibrosis, accompanied by a reduction in liver TG, serum ALT, and NEFA without changing other parameters." (PMID 38557493, 2024). "In line with the CEBPA/OPN axis modulation on liver fibrosis, hepatocyte HES1 induction–enhanced liver fibrosis similarly induces hepatocyte-derived OPN release." (PMID 38557493, 2024). "Postnatal deletion of CEBPA led to similar results but predominantly affected hepatic fibrosis rather than hepatic lipids." (PMID 38557494, 2024).
liver fibrosis (continued). "In this issue of the JCI, Yan and colleagues describe an ATF3/HES1/CEBPA/OPN pathway that links hepatocyte signals to fibrogenic activation of hepatic stellate cells and may provide new perspectives on therapeutic options for MASLD-induced liver fibrosis." (PMID 38557494, 2024).
ovarian carcinoma (12 papers, 2006 to 2025). A malignant neoplasm originating from the surface ovarian epithelium. "Low expression of the CEBPA transcription factor is associated with poorer overall survival and growth and progression phenotypes in ovarian cancer cell lines, and has been shown to repress WNT signaling." (PMID 39131380, 2024). "Here, we aimed to evaluate the prevalence of CEBPA gene mutations and polymorphisms in ovarian cancer patients, and also to look for associations between genetic alterations found and changes in the CEBPA mRNA expression levels." (PMID 27602952, 2016). "The possible reason for our analysis is that CEBPA has an extensive mutation in human tumors, and the mutation rate of CEBPA in ovarian cancer may have a higher mutation rate, thus inhibiting the anti-proliferative effect of CEBPA." (PMID 35284484, 2022). "Therefore, we believe that the overexpression of CEBPA can be regarded as a diagnostic molecule in ovarian cancer patients and can be considered as a target for ovarian cancer treatment." (PMID 35284484, 2022). "We evaluated the clinical significance of the two most common CEBPA gene polymorphisms identified herein, c.690G>T, p.(Thr230Thr) and c.584_589dupACCCGC, p.(His195_Pro196dup), in ovarian cancer patients treated with platinum/cyclophosphamide (PC) or taxane/platinum (TP) compounds." (PMID 27602952, 2016). "Clinicians can consider measuring the expression level of CEBPA when treating patients with ovarian cancer, which is helpful to evaluate the prognosis of patients and improve their living standards." (PMID 35284484, 2022). "According to the median expression of CEBPA level, ovarian cancer patients were divided into CEBPA low expression and CEBPA high expression." (PMID 35284484, 2022). "The mechanism of action of CEBPA in ovarian cancer needs further study, and more large-scale studies are needed to explore the relationship between the expression level of CEBPA and the pathobiological characteristics." (PMID 35284484, 2022). "Relationship between the expression of CEBPA and the pathobiological characteristics of ovarian cancer patients [n (%)]." (PMID 35284484, 2022). "CEBPA gene expression in ovarian cancer patients was evaluated at the RNA level with Reverse Transcription quantitative PCR (RT-qPCR)." (PMID 27602952, 2016). "Herein, CEBPA overexpression was significantly correlated with poor prognosis and prediction of ovarian cancer patients, likely due to an oncogenic role that CEBPA apparently acquires in this neoplasm." (PMID 27602952, 2016). "This is the first study assessing the clinical impact of CEBPA gene status and expression on the ovarian cancer outcome." (PMID 27602952, 2016). "This is the first study to investigate the presence and significance of expression and gene status of CEBPA in ovarian cancer." (PMID 27602952, 2016). "However, the results of this study need to be verified by more patients, to further explore the specific mechanism of CEBPA expression in ovarian cancer." (PMID 35284484, 2022). "According to our results, among ovarian cancer patients, the median survival time of patients with CEBPA high expression is shorter than that of patients with CEBPA low expression, and the overexpression of CEBPA level constitutes a factor of poor prognosis of ovarian cancer patients." (PMID 35284484, 2022). "CEBPA is expected to become a new biomarker for diagnosing and evaluating the prognosis of ovarian cancer, which may play a role in the treatment choice of patients with ovarian cancer." (PMID 35284484, 2022). "The results of real-time quantitative PCR showed that the expressions of CEBPA mRNA in ovarian tissues of patients with normal ovary, epithelial ovarian cyst, ovarian borderline tumor, and ovarian cancer were 0.95 ± 0.90, 1.08 ± 0.92, 3.56 ± 0.86, and 4.13 ± 0.87, respectively." (PMID 35284484, 2022). "CEBPA has involved the occurrence of ovarian cancer through gonadotropin and other related ways." (PMID 35284484, 2022).
ovarian carcinoma (continued). "To determine whether CEBPα could act as a positive regulator of DIRAS3 transcription during amino acid deprivation in A2780 ovarian cancer cells, we performed chromatin immunoprecipitation experiments following starvation for 2–4 h." (PMID 31052266, 2019). "In summary, we show here for the first time that the c.690G>T SNP (rs34529039) in the CEBPA gene, along with CEBPA overexpression at the mRNA level, constitute factors of poor prediction and prognosis in ovarian cancer patients treated with DNA-damaging agents." (PMID 27602952, 2016). "This is the first study providing evidence that the c.690G>T, p.(Thr230Thr) (rs34529039) polymorphism of the CEBPA gene, together with up-regulation of its mRNA expression, are negative factors worsening ovarian cancer outcome." (PMID 27602952, 2016). "Up to now, there has been no report describing how CEBPA is expressed in ovarian cancer tissues, and how the change of its expression affects the occurrence, prognosis of ovarian cancer." (PMID 35284484, 2022). "When CEBPα was knocked down with siRNA, we observed that nutrient deprivation was no longer able to upregulate DIRAS3 mRNA expression across several ovarian cancer cell lines and this correlated with a decrease in autophagy induction as determined by immunofluorescence staining of LC3 puncta." (PMID 31052266, 2019). "For the first time, we suggest here that both the c.690G>T SNP and overexpression of CEBPA mRNA are negative prognostic and predictive factors in ovarian cancer patients treated with DNA-damaging agents (the PC regimen)." (PMID 27602952, 2016). "To date, there are no data in the literature showing how alterations in the CEBPA gene sequence and its expression may affect ovarian cancer prognosis and tumor response to chemotherapy." (PMID 27602952, 2016).
acute leukemia (11 papers, 2010 to 2025). A clonal (malignant) hematopoietic disorder with an acute onset, affecting the bone marrow and the peripheral blood. "Here, we demonstrate that activating mutations in the granulocyte colony stimulating factor receptor (CSF3R), cooperate with loss of function mutations in the transcription factor CEBPA to promote acute leukemia development." (PMID 31784538, 2019). "Amongst acute leukemia patients in our cohort, one patient had RUNX1::RUNX1T1 translocation, while another had a biallelic CEBPA mutation, both of which are known to co-occur with CSF3R alterations." (PMID 40806796, 2025). "Previous studies have found that TRIB1 can affect the occurrence of acute leukemia through the mitogen-activated protein kinase/extracellular signal-regulated kinase pathway and CCAAT enhancer-binding protein alpha (C/EBPα)." (PMID 34811364, 2021). "Obtained results indicate a significant dissimilarity in CEBPA transcript level between the two acute leukemias (P < 0.0000), in particular investigated ALL group presented lower CEBPA expression." (PMID 31666608, 2019).
lipodystrophy (11 papers, 2013 to 2024). A congenital or acquired disorder characterized by abnormal loss or redistribution of the adipose tissue in the body. "The A-ZIP transgenic animals carry a dominant negative form of cEBPα leading to a block in adipogenesis resulting in severe congenital lipodystrophy." (PMID 32452759, 2020). "For two lipodystrophy genes, BSCL2 and AGPAT2, sub-clusters with PLIN1 and CEBPA identifed by morphological similarity were validated by independent experiments as novel protein–protein and gene regulatory interactions." (PMID 30940487, 2019). "Examination of the raw images of CEBPA/AGPAT2 ablated cells revealed cells with decreased lipid accumulation compared to controls, but did not appear distinctive on manual visual inspection in comparison to ablation of other lipodystrophy genes such as PPARG." (PMID 30940487, 2019). "This Cebpα construct can bind to DNA but does not have an activation domain and the transgenic animals develop a severe lipodystrophy, similar to that in patients with generalized lipodystrophy, with little detectable adipose tissue and severe metabolic abnormalities." (PMID 32452759, 2020).
prostate carcinoma (11 papers, 2006 to 2024). A carcinoma that arises from epithelial cells of the prostate gland. "A recent study found that CEBPA promotes castration-resistance and AR signaling in prostate cancer through a direct protein interaction with AR; this suggests that co-targeting CEBPA and AR may be one approach to block AR in either castration-resistant or enzalutamide-resistant tumors." (PMID 29340039, 2017). "Interaction of CEBPA and PARP1 has been previously demonstrated in prostate cancer, however, we could not validate their interaction in AML cells due to overlap with unspecific antibody/bead complex signals." (PMID 33911178, 2021).
asthma (10 papers, 2011 to 2026). "We have earlier reported that an impaired translation-initiation of the CEBPA mRNA in BSM cells of asthma patients was associated with the decreased expression of the translation regulator eIF4E." (PMID 22500186, 2012). "Aberrant translation of the CEBPA gene, which is implicated in the forward direction, has also been associated with causing bronchial smooth muscle cells—a tissue that plays a key role in asthma—to proliferate faster." (PMID 40504147, 2025). "The observed diminished expression of C/EBPα in BSM cells of asthma patients is mainly due to posttranscriptional regulation affecting the translation of the CEBPA mRNA." (PMID 22500186, 2012). "Previous studies showed that CEBPA expression was absent in cultured ASMCs from subjects with asthma." (PMID 40205616, 2025). "The lack of CEBPA expression was associated with the failure of glucocorticoids to inhibit ASMC proliferation, suggesting that it could play a role in steroid-resistant asthma." (PMID 40205616, 2025).
chronic myeloid leukemia (9 papers, 2019 to 2025). "CEBPA also promoted the development of chronic myelocytic leukemia by glycogen synthase kinase-3 (GSK3) and Wnt/β-catenin signaling." (PMID 39569391, 2025). "Besides, studies have reported that CEBPA could promote the progression of chronic myelocytic leukemia (CML) via the Wnt/β-catenin signaling pathway." (PMID 39569391, 2025). "Some patients had a history of CNL or atypical chronic myeloid leukemia, whereas others presented de novo with CBF or CEBPA alterations." (PMID 41423432, 2025).
liposarcoma (9 papers, 2008 to 2022). A usually painless malignant tumor that arises from adipose tissue. "Hypermethylation of CEBPA and p16INK4a is observed in liposarcoma and causes downregulation and enhances tumor development." (PMID 35008848, 2021). "CEBPA and p16INK4a act as suppressors of liposarcoma to induce apoptosis and suppress proliferation and dedifferentiation." (PMID 35008848, 2021). "CCAAT/enhancer-binding protein alpha (CEBPA) methylation was observed in 24% of patients with dedifferentiated liposarcomas." (PMID 35008848, 2021). "Demethylating agent treatment improves the expression of CEBPA in dedifferentiated liposarcoma cells and plays a role in antitumor development." (PMID 33498189, 2021). "Dedifferentiated liposarcomas (DLPS) harbor histone deacetylase 1 (HDAC1) mutations in 8.3% of cases, and liposarcoma methylomes show alteration in differentiation genes, including CCAAT/Enhancer Binding Protein Alpha (CEBPA) methylation in 24% of cases." (PMID 28654693, 2017). "Adipocyte dedifferentiation in the pathogenesis of human liposarcomas is supported by the fact that methylation of the gene CEBPA, which encodes one of the key adipogenic transcription factors CCAAT/enhancer binding protein α (C/EBPα), is observed in 24% of DDLPS patients." (PMID 31775295, 2019). "CEBPA (CCAAT/enhancer binding protein, alpha) methylation is seen in 24% of dedifferentiated liposarcomas." (PMID 33498189, 2021).